IL21 (interleukin 21)
Diseases named in the same sentence as IL21 in open-access papers (continued):
Sharing a sentence is not in itself a finding about the gene and the disease.
ovarian carcinoma (13 papers, 2010 to 2024). A malignant neoplasm originating from the surface ovarian epithelium. "Modulation in the IL-21 and IL-22 system may affect the course of the inflammatory process that accompanies the development of cancer, which may prove useful in the development of new diagnostic and therapeutic strategies used in patients with ovarian cancer, which requires further studies." (PMID 34300224, 2021). "The analyses conducted so far on the evaluation of IL-21 and IL-22 in ovarian cancer have been interesting and induce further research." (PMID 34300224, 2021). "Then, the concentration of IL-21 in serum and the peritoneal fluid of women with ovarian cancer depending on the degree of histopathological differentiation of the cancer was analyzed." (PMID 34300224, 2021). "Recent studies have shown that interleukin 21 and interleukin 22 play an important role in the pathogenesis of cancer, which role in the formation and development of ovarian cancer is still not fully understood." (PMID 34300224, 2021). "The concentration of Il-21 was determined in the serum and peritoneal fluid of women with ovarian cancer." (PMID 34300224, 2021). "The concentration of IL-21 and IL-22 in the serum and in the peritoneal fluid of women with ovarian cancer varied depending on the degree of histopathological differentiation of the cancer and showed statistical variability compared to controls." (PMID 34300224, 2021). "Intravenous injection of human umbilical cord blood stem cells (UCBSC) engineered to express murine IL-21 inhibited the growth of human ovarian cancer cells xenotransplanted in nude mice and prolonged survival." (PMID 25961061, 2015). "In nude mice, human ovarian cancer cells genetically modified to secrete both IL-21 and GM-CSF enhanced NK cell activity, IFN-γ, and tumor necrosis factor- (TNF-) α levels resulting in inhibition of tumor growth." (PMID 25961061, 2015). "The data indicated that hUCMSCs were developed appropriately, which assists in the further study of hUCMSCs as vehicles for IL-21 delivery via lentiviral to develop therapeutic effect on SKOV3 ovarian cancer xenograft-bearing nude mice." (PMID 24444073, 2014). "The present study was aimed to investigate effect of hUCMSCs as vehicles for a constant source of transgenic interleukin-21 (IL-21) on ovarian cancer in vivo." (PMID 24444073, 2014). "This has further been enhanced by a recent study showing that the antitumor effect is increased by human ovarian cancer cells secreting IL21 alone or in combination with GM-CSF." (PMID 21318181, 2010). "A statistically significantly lower concentration of IL-21 in the serum of women with ovarian cancer was demonstrated compared to the concentration in the control group (p < 0.001), where Q1 and Q3 were respectively: 722.19 and 909.60 with a median of 793.59 pg/mL." (PMID 34300224, 2021). "The results implied that the secreted IL-21 from hUCMSCs-LV-IL-21 may assist in the inhibition of ovarian cancer growth in the mouse model by down-regulation of β-catenin and cyclin-D1 expression in Wnt/β-catenin signal transduction pathway." (PMID 24444073, 2014). "In the study, we first constructed the recombinant lentiviral vector for lasting the expression of IL-21, and then the hUCMSCs transducted by IL-21 gene packaged lentivirus had been injected into mouse ovarian cancer model to assess the effect of hUCMSCs-LV-IL-21 on ovarian cancer in vivo." (PMID 24444073, 2014). "The animal experiment results indicated that transferring CD34+ UCBSC- IL-21 into A2780 ovarian cancer xenograft-bearing nude mice augmented the therapeutic effect on ovarian cancer, however, IL-21 expression was gradually decreased in the mouse tumor sites 21 days posttransplantation." (PMID 24444073, 2014). "Cytokines such as IL-12 and IL-21 are currently considered for their therapeutic potential in other types of cancer and may have the same effect in ovarian cancer." (PMID 21318181, 2010).
ovarian carcinoma (continued). "Local and systemic changes in the immune system with the participation of soluble mediators IL-21 and IL-22 indicate the participation of these parameters in the development of ovarian cancer and may participate in pro and anti-inflammatory activation involving the tested cytokines." (PMID 34300224, 2021). "Our studies showed a statistically significantly lower concentration of IL-21 in the serum of women with ovarian cancer compared to the concentration in the control group, which indicates the participation of the tested cytokine in the immune response against ovarian cancer cells." (PMID 34300224, 2021). "Moreover, it was shown that the concentration of IL-21 in the peritoneal fluid of women with ovarian cancer differed between the grades of G2 and G3, which proves that the secretion of IL-21 is related to the histological differentiation of ovarian cancer also in this biological fluid." (PMID 34300224, 2021). "Furthermore, we further identified whether IL-21 was expressed in ovarian cancer tissues in the mice." (PMID 24444073, 2014). "The hUCMSCs were engineered to express IL-21 via lentiviral vector- designated ‘hUCMSCs-LV-IL-21’, and then were transplanted into SKOV3 ovarian cancer xenograft-bearing nude mice." (PMID 24444073, 2014). "After 21 days of induction with SFTG36 (SCF, FLt-3L, TPO, GM-CSF, IL-3 and IL-6), IS721 (IGF-1, SIS3, IL-7 and IL-21) and IL-15/Hsp70 media, NK cells phenotypes were studied and their cytotoxicity against K562 human erythroleukemia cells and SKOV3 ovarian carcinoma cells was analyzed." (PMID 34098947, 2021). "Here, we show that hUCMSCs themselves do not form tumors, and that tumor growth in ovarian cancer bearing mice is significantly inhibited following systemic administration of IL-21-expressing hUCMSCs." (PMID 24444073, 2014). "To further analyze the mechanisms of hUCMSCs- LV-IL-21 therapy for ovarian cancer in mice, we designed an experiment to find out whether the serum cytokines of IL-21, IFN-γ, and TNF-α were changed in the mice treated with hUCMSCs-LV-IL-21." (PMID 24444073, 2014).
pancreatic cancer (13 papers, 2018 to 2025). "In summary, high numbers of intratumor IL-21+ infiltrates, aberrant expression of IL-21R, and its downstream target Blimp-1 in pancreatic tumor cells are associated with disease progression of PDAC." (PMID 31540511, 2019). "constructed recombinant vaccinia virus VVL-21 expressing B5R and interleukin-21 (IL-21) genes to combat pancreatic cancer." (PMID 35686109, 2022). "Taken together, the data indicate that in pancreatic tumor cells IL-21 induces capacities required for metastasis formation in a Blimp-1-dependent manner." (PMID 31540511, 2019). "Because IL-21 is a major cytokine released by Th17 helper cells, the latter prevalent in PDAC, the infiltration of IL-21+ immune cells and the expression of the respective receptor in pancreatic tumor tissue was analyzed." (PMID 31540511, 2019). "In vitro data using pancreatic tumor cells lines provided a possible explanation: IL-21 activated ERK and STAT3 pathways and upregulated Blimp-1." (PMID 31540511, 2019). "TIL were expanded from primary (P) or metastatic lesions (ML) in medium containing IL-2, IL-15 and IL-21 from 2 patients with pancreatic cancer (PDAC), 1 patient with glioblastoma (GB), 1 patient with fibrosarcoma (FS) and 1 patient with uveal melanoma (UVM)." (PMID 30400835, 2018). "Thus, we hypothesize that IL-21 exhibits a biologically relevant and generally positive effect on circulating immune cells in patients with pancreatic cancer, associated with expansion of certain TCR specificities, such as specific mesothelin epitopes, described in this report." (PMID 29854291, 2018). "Recently, we described the expression of the receptor for IL21 on pancreatic tumors, and most importantly, we found that both the presence of IL21 positive T cells and the expression of the respective receptor were associated with a shorter survival time of the patients." (PMID 31948053, 2020). "Expression of the receptor for IL21 by pancreatic tumor cells was shown previously by our group and could be confirmed in this study for the here used cohort of patients." (PMID 31948053, 2020). "Moreover, transduction of IL-21 constructs into pancreatic cancer cell lines resulted in anti-tumor effects when the cells were implanted into T cell-free NOD/SCID mice." (PMID 31540511, 2019). "Interestingly, these patients also have high numbers of IL-21 positive T cells, although the function of IL-21 and its receptor in human pancreatic cancer was unclear." (PMID 31540511, 2019). "Hence, to evaluate the role of IL-21 in human pancreatic cancer, in the present study we analyzed tissue specimen of patients with PDAC and in vitro experiments with pancreatic cell lines as well as an avian xenograft model as an in vivo correlate." (PMID 31540511, 2019). "Therefore, we decided to use IL-21 in the experiments in order to investigate the ‘conditioning effect’ of IL-21 on mesothelin-specific T cells from patients with pancreatic cancer." (PMID 29854291, 2018). "In addition, we have previously reported a cytokine cocktail, consisting of IL-2, IL-15 and IL-21, that leads to the accumulation of central memory tumor infiltrating T-cells (TILs), obtained from patients with glioblastoma as well as pancreatic tumors." (PMID 29854291, 2018). "IL-21-armed OVV VΔTK-STCΔN1L-IL-21 was injected into subcutaneous, orthotopic and disseminated mouse models of pancreatic cancer, and phosphoinositide 3-kinase δ (PI3Kδ) inhibitor CAL-101 was used to inhibit the virus uptake by macrophages." (PMID 40469178, 2025). "Follicular helper T cells can promote an immunoactive pancreatic cancer microenvironment by secreting CXCL13 and IL-21." (PMID 35468838, 2022). "Freshly harvested tumor tissues (colorectal and pancreatic cancer) were procured for TIL expansion using IL-2, IL-15 and IL-21." (PMID 30400835, 2018).
pancreatic cancer (continued). "Despite the demonstrated potential of viruses combining immunizing factors like VVL-GL21 co-expression GM-CSF/IL-21, the absence of T-cell infiltration and the defective memory response in pancreatic cancer still pose an unsolved issue." (PMID 40299475, 2025). "Pancreatic cancers—but not healthy pancreatic tissue—expressed receptors for IL21 and IL26, a finding that could be confirmed in pancreatic cell lines." (PMID 31948053, 2020). "In the present study, we show for the first time that IL-21 conditioning enhances mesothelin-specific T-cell responses, reflected by IFN-γ production in peripheral blood mononuclear cells, which correlates with increased survival of patients with pancreatic cancer who undergo surgery." (PMID 29854291, 2018).
colorectal cancer (12 papers, 2014 to 2026). A primary or metastatic malignant neoplasm that affects the colon or rectum. "A study of sporadic colorectal cancer has shown that IL-21 deficiency may be associated with impaired STAT3 and NFκB signaling activity in immune and neoplastic cells." (PMID 35410210, 2022). "Previously, the role of miR-155 in the pathogenesis of IBD and colorectal cancer were mentioned, therefor, clarifying the association of this miRNA with IL-21 in CAC may be helpful." (PMID 35410210, 2022). "BACKGROUND: This study aimed to elucidate the proliferative and migratory roles of interleukin-21 (IL-21) in HCT-116 and HT-29 colorectal cancer cells using a loss-of-function gene approach." (PMID 41957653, 2026). "Knockdown of IL-21, which is overexpressed in human colorectal cancer and CAC mice, can reverse the overexpression of IL-6 and IL-17A in CAC mice." (PMID 36339623, 2022). "CONCLUSION: The pro-tumourigenic properties of IL-21 could serve as a biomarker of tumour aggressiveness in colorectal cancer and provide insights for the development of advanced cancer therapies." (PMID 41957653, 2026). "Furthermore, IL-21 signalling was found to promote the proliferation and migration of colorectal cancer cells by suppressing the activation and phosphorylation of ERK1/2 and STAT3." (PMID 41957653, 2026). "In addition, recombinant IL-21 has been tested as an anti-tumor agent in various clinical trials, achieving good results in colorectal cancer and metastatic renal cell carcinoma." (PMID 38833177, 2024). "Furthermore, colorectal cancer patients with higher IL-21 levels had longer overall survival." (PMID 35884974, 2022). "In the future, histological staining will be performed on patients with ablated recurrent colorectal cancer liver metastases to determine the expression distribution of IL-21R, which provides a basis for MWA combined with IL-21 treatment." (PMID 38833177, 2024). "The absence of IL-21 in colorectal cancer TME seemed to shift the balance between Th17 and Th1, as well as between macrophages M2 and M1, towards the latter." (PMID 35884974, 2022).
chronic lymphocytic leukemia (11 papers, 2013 to 2026). "CpG oligodeoxynucleotides (ODNs) upregulate the interleukin-21 receptor (IL21R) and enhance IL-21-mediated cytotoxicity in chronic lymphocytic leukemia (CLL) B cells." (PMID 26158860, 2015). "Studies in chronic lymphocytic leukemia (CLL) cells have shown that treatment with interleukin-21 promotes Stat5 phosphorylation in natural killer cells which enhanced antibody-dependent cellular cytotoxicity (ADCC) against rituximab-coated CLL cells in vitro." (PMID 24304724, 2013). "Although CAR T cells with activation-dependent IL-21 secretion (NFAT promoter-IL-21) displayed increased tumor infiltration in a chronic lymphocytic leukemia CDX model, no obvious improvement in anti-tumor efficacy has been reported." (PMID 36059449, 2022). "IL-21 and IL-21R are emerging as promising targets for novel cytokine-based immunotherapies in many diseases, including SLE, primary immunodeficiency (PID), chronic lymphocytic leukemia (CLL), multiple myeloma (MM), and lymphoma." (PMID 31921177, 2019). "Similarly, a recent study using NK cells from patients with B-cell chronic lymphocytic leukemia demonstrated enhanced cytotoxicity and ADCC when the cells were stimulated with IL-21 and rituximab, compared to control or rituximab treatment alone." (PMID 23825648, 2013).
colon carcinoma (11 papers, 2011 to 2025). "Four Apcmin/+ mice had to be killed before the end of the scheduled treatment, because of intestinal occlusion caused by large colonic tumors, whereas all the IL-21-KO-Apcmin/+ mice survived until the end of the study." (PMID 25839161, 2015). "The first evidence of IL-21 antitumor activity in vivo was shown in a murine model, when colon carcinoma cells transduced to express IL-21 were rejected, the antitumor effects being dependent on T and NK cells, in this case." (PMID 38638431, 2024). "IL-21 is produced by CXCL13 + CD4 + T cells in human colon cancer, liver cancer, and non-small cell lung cancer." (PMID 38833177, 2024). "Using a subcutaneous mouse model of colon cancer, we confirmed a combination of recombinant free IL-21 and anti-PD-1 antibody (mAb) dosed concurrently, extended survival, in an established tumor model." (PMID 32457754, 2020). "To determine the cellular origin of IL21 in human tumor tissues, we analyzed public scRNA-seq data of 8,530 T cells from 12 patients with colon cancer, 9,055 T cells from 14 patients with non–small cell lung cancer, and 5,063 T cells from 6 patients with liver cancer." (PMID 37546701, 2023). "Moreover, colonic tumors developing in wild-type mice exhibited an increased infiltrate of both M2 macrophages and MDSC than those grown in IL-21-deficient mice." (PMID 23109839, 2012). "Another study showed that VVLΔTKΔN1L-mIL-21, an OVV expressing IL-21, exhibited more potent anti-tumor effects than VVLΔTKΔN1L-RFP in a C57 mouse colon cancer model." (PMID 40469178, 2025). "We showed that IL21 is produced by Tfh cells in the human TME, particularly in colon cancer." (PMID 37546701, 2023). "In contrast, using a CT26 colon carcinoma model to evaluate the combinatorial therapy, only IL-21 and mAb CTLA-4 combination showed efficient results, five of eight mice presented complete regression of tumor with the IL-21 and mAb PD-1 combination having no antitumor effects in this model." (PMID 38638431, 2024).